TLR4 (toll like receptor 4)
Diseases named in the same sentence as TLR4 in open-access papers (continued):
Sharing a sentence is not in itself a finding about the gene and the disease.
gastric cancer (continued). "Seventeen percent of gastric carcinoma patients in the initial study and 15% of the noncardia gastric carcinoma patients in the replication study had 1 or 2 TLR4 variant alleles versus 8% of both control populations (combined OR = 2.3; 95% CI = 1.6–3.4)." (PMID 25945326, 2015). "We found significantly positive correlations between the two selected TLR4 polymorphisms and increased risks of gastric cancer in Caucasians, but not in non-Caucasian." (PMID 25290654, 2014). "In the subgroup meta-analyses, we found significantly positive correlations between the two selected TLR4 polymorphisms and increased risks of gastric cancer in Caucasians, but not in non-Caucasian." (PMID 25290654, 2014). "The recognition of TLR4 by its ligand results in a cascade reaction including the IL-1R family activation and followed by the activation of NF-κB, which is a key mediator of inflammation-induced gastric cancer development." (PMID 25290654, 2014). "The aim of this study was to determine whether the polymorphisms of TLR4 and TLR9 are associated with susceptibility to gastric carcinoma and its prognosis." (PMID 23776537, 2013). "It was found that CXCL1/CXCR2 recruits PMN-MDSCs, and S100A8/A9 increases CXCL1 expression in gastric cancer (GC) through the TLR4/p38 MAPK/NF-κB pathway." (PMID 39990210, 2025). "Recently, the circulating levels of soluble forms of TLR2, TLR4, and TLR9 were positively associated with advanced stages of gastric cancer, including an upregulation of the protein levels on circulating immune cells in patients with gastric cancer compared to those with premalignant lesions." (PMID 40362298, 2025). "Gastric cancer cell‐derived exosomes induce autophagy and protumor activation through the HMGB1/TLR4/NF‐кB signaling pathway to enhance the growth and migration of GC cells." (PMID 38685971, 2024). "Therefore, we suggest that TLR4 may be an important target in gastric cancer TME, where immune responses and ferritinase interactions are probably based on this key genes." (PMID 36936437, 2023). "Furthermore, while H. pylori LPS as well as E. coli LPS was shown to augment the growth of gastric cancers, all of which expressed TLR4, the neutralization of TLR4 with specific antibodies almost completely abrogated H. pylori-induced gastric cancer cell proliferation." (PMID 33217986, 2020). "Furthermore, tumor-bearing nude mice and clinicopathology were used to verify that the LPS/TLR4/CXCR7 pathway may be critical during gastric cancer development." (PMID 30636642, 2019). "We did not observe associations between the TLR4 genotypes and gastric cancer." (PMID 26161647, 2015). "In addition, the previous meta-analyses did not cover all eligible publications related to gastric cancer and thus decreased the efficacy and probability of detecting the authentic association between TLR4 gene polymorphisms and gastric cancer risk." (PMID 25290654, 2014). "Two variations in the 5′-flanking region of TLR4 (rs1927914 T > C and rs10759932 T > C) were genotyped by using the PCR-restriction fragment length polymorphism (RFLP) assay in a case-control study of 1,053 incident gastric cancer cases and 1,100 cancer-free controls in a Chinese population." (PMID 23554619, 2010). "In gastric cancer (GC) patient models, compared to healthy volunteers, the expression of TLR-2, TLR-3, TLR-4, and TLR-9 was significantly elevated in GC patients, with higher TLR expression observed in more advanced GC subtypes." (PMID 41488647, 2025). "A recent mechanistic study showed that in gastric cancer, hypoxic tumor microenvironments stimulate NET formation via the HMGB1/TLR4/p38 MAPK pathway, and that elevated NET levels are associated with poorer prognosis." (PMID 41333516, 2025). "In gastric endothelial cells, BGN enhances NF-κB binding to the HIF-1α promoter via TLR2 and TLR4 signaling, resulting in increased VEGF expression and enhanced migration of gastric cancer cells." (PMID 41465449, 2025).
gastric cancer (continued). "In summary, gastric cancer-exosomes promote autophagy and N2 neutrophil polarization via the HMGB1/TLR4/NF-кβ signaling." (PMID 40443670, 2025). "The secondary outcomes were the expression levels of TLR4 (Toll-like receptor), IL-6 and TNF-α in gastric cancer tissue." (PMID 38720250, 2024). "In gastric cancer (GC), TLR2, TLR3, TLR4, and TLR9 are crucial for modulating immune response and tumor progression." (PMID 39451226, 2024). "The blockade of COX-2 production and TLR4 signaling attenuated the LPS- and HM-induced PGE2 and IL-6 secretion in the human gastric cancer epithelial cell line AGS." (PMID 37658354, 2023). "TLR4 and KRAS, as common genes for immune infiltration and ferroptosis, are involved in gastric carcinogenesis and play an important role in gastric cancer progression." (PMID 36936437, 2023). "TLR4 plays a major role in the inflammation of the superficial gastric lining, whereas TLR9 plays a major role in the inflammation of gastric cancer." (PMID 36825088, 2023). "In the current study, we investigated the gastroprotective effects of HM based on TLR4/COX2 expression, PGE2 and IL-6 secretion using the classical in vitro model for gastric ulcer disease, the gastric carcinoma epithelial cell line AGS." (PMID 37658354, 2023). "Toll-like receptor 4 plays an important role in the Toll-like receptor signalling pathway, which could mediate an inflammatory response in the gastric epithelia induced by H. pylori and sequentially contribute to the initiation and progression of gastric cancer cells." (PMID 36299773, 2022). "In in vitro experiments, modification of MCEMP1 can affect the invasiveness and metastasis of gastric cancer cells by regulating EMT, in which TLR4/NOD2/NF-κB was involved." (PMID 35378772, 2022). "Meanwhile, the derived exosomes contain HMGB1 protein, which activates the NF-κB pathway through the interaction with toll-like receptor 4 (TLR4), promotes the autophagy of neutrophils, and ultimately induces the migration of gastric cancer cells." (PMID 36741380, 2022). "In the present study, L. plantarum induced apoptosis in a gastric cancer cell line (AGS) through up-regulating PTEN, Bax, TLR4 and down-regulating Akt." (PMID 36147842, 2022). "The level of resistin, which is a regulator of inflammation, activates TLR signaling and toll-like receptor 4 cascade in STAD and is positively correlated with gastric cancer." (PMID 36008864, 2022). "After meta-analysis of GC gene expression profile chip, it was found that 7 of these genes, including AKR1B1, CTSK, MMP2, TLR4, ADRB2, PDE1C, and PTGER3, had significant differences in gastric cancer tissues." (PMID 34646828, 2021). "In an attempt to extend our observations to other cancer types, we analyzed the correlation of TLR4 expression and STAT3 phosphorylation in human liver cancer, lung cancer and stomach cancer tissues using tissue microarray assays." (PMID 32312954, 2020). "LPS exposure increased the expression of CXCR7 in gastric cancer SGC7901 cells, which highly express TLR4/MD-2." (PMID 30636642, 2019). "The expression rate of TLR4, MD-2 and CXCR7 in gastric cancer tissues was 68% (102/150), 54% (81/150) and 59.3% (89/150), respectively, and these rates were significantly different from those in normal gastric tissues." (PMID 30636642, 2019). "We used IHC to analyze the clinicopathologic relevance of TLR4, MD-2 and CXCR7 expression in gastric cancer tissues." (PMID 30636642, 2019). "In a study among 106 gastric adenocarcinoma patients, TLR3, TLR4, and TLR9 were highly expressed in gastric cancer tissues and survival worsened among patients with a high TLR3 expression." (PMID 31467388, 2019). "The results indicated that TLR4 and CXCR7 expression is related to gastric cancer growth and metastatic potential." (PMID 30636642, 2019). "The expression levels of TLR4, MD-2 and CXCR7 were closely related to gastric cancer TNM stage and lymph node metastasis." (PMID 30636642, 2019).
gastric cancer (continued). "The aim of our study was to evaluate potential associations between the presence of gastric cancer (GC) and high risk atrophic gastritis (HRAG) and polymorphisms of genes encoding Angiotensin converting enzyme (ACE), Nod-like receptor 1 (NOD1), Toll-like receptor 4 (TLR4) and FAS/FASL." (PMID 21864388, 2011). "Recently, the tissue expressions of TLR1, TLR2, TLR4, TLR5, TLR7 and TLR9 as potential prognostic biomarkers in gastric cancer were reported, showing a positive correlation between each other and a high expression of each studied TLR in tumors with an intestinal-type histology." (PMID 40362298, 2025). "Another agent is Sophoridine which has been reported to suppress M2 polarization and increase M1 polarization through TLR4/IRF3 pathway and inhibit TAMs infiltration by downregulating CCR2 expression in gastric cancer TME, thereby improving the cytotoxicity function of CD8 + T cells." (PMID 39003350, 2024). "Similarly, in the inflammatory microenvironment of gastric cancer, Helicobacter pylori activates downstream inflammatory factors, like IL-6, IL-10, and COX-2, through TLRs (mainly TLR2 and TLR4), thus initiating a series of inflammatory responses." (PMID 37153547, 2023). "In addition, in gastric cancer, S100 calcium binding proteins S100A8/A9 inhibit CD8+ T cell glycolysis through the Toll like receptor 4 (TLR4)/AKT/mTOR pathway, affecting their proliferation and eventually leading to failure." (PMID 37422501, 2023). "Through TLR4/PI3K/Akt signaling, P. acnes encourages M2 macrophage polarization in gastric cancer." (PMID 36825088, 2023). "The role of TLR4 in activating the COX-2/PGE2 pathway in murine macrophages, intestinal epithelial cells, auditory cells, Barrett’s esophagus, and in human gastric carcinoma cells has been reported." (PMID 37658354, 2023). "For example, METTL3 activates dendritic cells and initiates activation of cytotoxic T lymphocytes by increasing m6A levels of CD40, CD80, and TLR4; METTL3 overexpression promotes gastric cancer progression (GC) and liver metastasis through angiogenic and glycolytic pathways." (PMID 35281520, 2022). "The ASCL2 shows a negative correlation with inflammation, and TLR4 reveals a positive correlation with gastric cancer." (PMID 36008864, 2022). "Moreover, higher TLR4 and CXCR7 expression levels were found in gastric cancer tissues than in paracancerous normal tissues." (PMID 30636642, 2019). "Moreover, higher TLR4, MD-2 and CXCR7 expression was detected in gastric cancer tissues than in paracancerous normal control tissues." (PMID 30636642, 2019). "Nevertheless, the biological function and regulation of CXCR7 and its relationship with TLR4 and MD-2 in gastric cancer are still not completely understood and are therefore worthy of study." (PMID 30636642, 2019). "Thus, we aimed to evaluate the tissue expressions of TLR1, TLR2, TLR4, TLR5, TLR7, and TLR9 as potential prognostic biomarkers in gastric cancer." (PMID 31467388, 2019). "TLR4 may participate in cancer-related inflammation via e.g., up-regulation of an oncogenic protein Astrocyte-elevated gene-1 (AEG-1) in gastric cancer tissue." (PMID 28350359, 2017). "Further quantification of TLR4 staining intensity in these tissues revealed that TLR4 expression was elevated in gastric cancer tissues (70%), but not normal tissues (10%) (data not shown)." (PMID 26675260, 2016). "In this study, we did not detect TLR4+896G, TLR4+1196T, or TLR9 -1237C alleles in gastric cancer patients and healthy controls in the Chinese population." (PMID 23776537, 2013). "TLR expression especially TLR4, and TLR9, may act as a prognostic biomarker in gastric cancer." (PMID 39451226, 2024). "Increasing expression of TLR2, TLR4, TLR5, and TLR9 in gastric epithelia of children' gastritis; TLR4, TLR5, and TLR9 in adults' gastritis; TLR2, TLR4, and TLR5 in gastric dysplasia; and TLR4, TLR5, and TLR9 in gastric cancer (GC) is found." (PMID 35300405, 2022).
gastric cancer (continued). "However, the regulatory mechanism and relationship between TLR4-MD-2 and CXCR7 in promoting gastric cancer development remains unknown." (PMID 30636642, 2019). "TLR4+896G, TLR4+1196T, and TLR9 -1237C alleles may be very rare, at least in Chinese, Korean, and Japanese populations; thus, this gene may not be a candidate for determining gastric cancer susceptibility in this area." (PMID 23776537, 2013). "Therefore, our study aims to evaluate the expression of Toll-like receptors (TLR-2, TLR-3, TLR-4, and TLR-9) on NK and NKT-like cells in patients with gastric cancer (GC), compare these results with healthy volunteers (HV), and investigate variants depending on the cancer subtype." (PMID 39594809, 2024). "Similar to our findings, that study concluded that TLR4 and TLR9 expression levels did not significantly predict outcome in gastric cancer patients." (PMID 31467388, 2019). "In addition to TLR5, TLR1, TLR2, TLR4, TLR7, and TLR9 were also expressed in gastric cancer tissues, yet their expression levels did not function as prognostic biomarkers across the entire patient cohort." (PMID 31467388, 2019).
periodontitis (134 papers, 2008 to 2026). An acute or chronic inflammatory process that affects the tissues that surround and support the teeth. "Shared genetic risk factors between periodontitis and Alzheimer’s have also been proposed, such as polymorphisms in genes related to innate immunity and inflammatory response (e.g., TLR4, NLRP3, TREM2)." (PMID 40231144, 2025). "The A/G genotype of SNP -2570 of the TLR4 gene was identified as a risk factor for the development of periodontitis [OR = 2.28 (95% CI: 1.04–5.00)]." (PMID 40552316, 2025). "Our results indicate that P.g-OMVs inhibit osteogenic differentiation of BMSCs via the SAA3-mediated TLR4/MyD88/NF-κB axis, providing novel targets for the treatment of periodontitis-induced alveolar bone loss." (PMID 40791819, 2025). "The TLR4 Asp299Gly SNP (rs4986790) is a non-synonymous polymorphism implicated in altered infection responses across various diseases; however, its role in periodontitis remains controversial." (PMID 40723451, 2025). "Globally, our results point to a significant contribution of the polymorphism rs4986790 in the TLR4 gene in the pathogenesis of apical and chronic periodontitis." (PMID 40723451, 2025). "This study confirms that the presence of the A/G genotype of the SNP A-2570G of the TLR4 gene is a risk factor in the presence of bacteria such as C. acnes (3.7), S. anginosus (3.7), and S. gordonii (2.5) for developing periodontitis." (PMID 40552316, 2025). "It has been reported that in placentas of preeclamptic women with periodontitis, there is an association between P. gingivalis and P. intermedia with increased expression of TLR-4 and NF-κB." (PMID 40161970, 2025). "TLR4 plays a role in the immunological response associated with periodontitis by stimulating the release of inflammatory cytokines in response to bacterial infections." (PMID 39063437, 2024). "TLR4 has been shown to be closely implicated in inflammatory responses that caused gingivitis and periodontitis." (PMID 38007427, 2023). "The association of single nucleotide polymorphisms in the coding region of the Tlr4 gene with osteoporosis and chronic periodontitis supports the notion of a protective role of TLR4 in bone metabolism." (PMID 37596575, 2023). "Yu and coworkers investigated the association between single-nucleotide polymorphisms (SNPs) in toll-like receptor (TLR)-4 in Han Chinese patients with chronic periodontitis and COPD." (PMID 37762876, 2023). "Of note, in experimental mouse models of periodontitis, TLR4 loss of function inhibits the deleterious effect of periodontitis on the insulin signaling pathway, evidenced by the increased ratio of pAkt/Akt and decreased levels of TNF-α." (PMID 35327570, 2022). "In a periodontitis model in C3H/HeJ mice, reduced bone respiration was observed when TLR-4 deficiency prevailed." (PMID 36013115, 2022). "In pre-eclamptic women with periodontitis, the presence of P. gingivalis and P. intermedia was associated with the increase of TLR-4 and NF-κB expression in the placenta." (PMID 34281133, 2021). "Several studies have observed an association between periodontitis and the onset of AD, implicating the “leaky gum” in promoting toll-like receptor 4 (TLR-4) and TLR-2 mediated inflammation." (PMID 33800340, 2021). "Our findings indicated that periodontitis was associated with learning and memory impairment, probably induced by neuroinflammation via activating the TLR4/NF-κB signaling pathway." (PMID 32714134, 2020). "In meta-analysis studies, TLR4 896G allele was associated with the risk of developing periodontitis, in a recessive model and after stratification by ethnicity, only in Caucasians." (PMID 31281226, 2019). "A meta-analysis assessing the association between TLR4 polymorphisms and chronic periodontitis (CP) detected an association between TLR4C > G (rs7873784) allele and CP in Asians." (PMID 30837987, 2019).